PIK3CA (phosphatidylinositol-4,5-bisphosphate 3-kinase catalytic subunit alpha)
Diseases named in the same sentence as PIK3CA in open-access papers (continued):
Sharing a sentence is not in itself a finding about the gene and the disease.
breast tumors (continued). "Great effort has been directed to demonstrating the relevance of targeting the PI3K pathway in breast tumors driven by PIK3CA aberrations." (PMID 34298731, 2021). "Preclinical studies demonstrated that HER2 signaling largely relies on p110α rather than on other class-I PI3K isoforms, thus providing a strong rationale for therapeutic intervention and targeting of PIK3CA in HER2+ breast tumors." (PMID 34298731, 2021). "It has already shown robust activity in preclinical models of breast tumors with genetic alterations in PIK3CA." (PMID 34298731, 2021). "PIK3CA mutations were seen in 34.5% hormone receptor-positive (HR+), 22.7% in HER2 positive (HER2+), and 8.3% in basal-like breast tumors." (PMID 34769309, 2021). "For example, PIK3CA and KDR mutations are predominantly found in AS tumors of the breast (7/7 and 9/11 samples with mutations in these genes, respectively, were from breast tissue)." (PMID 34296746, 2021). "Moreover, PIK3CA mutations may sometimes harbor PTEN loss or HER2 overexpression in breast tumors." (PMID 33375317, 2020). "In conclusion, we have shown that FOXM1 expression is a biomarker of response and resistance to PI3Kα inhibition in ER+PIK3CA-mutant breast tumors." (PMID 32976773, 2020). "More recently, oncogenic PIK3CA activated multi-potency was found to induce breast tumor heterogeneity." (PMID 30659204, 2019). "SLC1A5, GLS, PYCR1 and PIK3CA were significantly expressed in breast tumours with high expression of SLC7A5 (p < 0.001), while the low expression of SLC7A5 was associated with high levels of p-mTORC1 (p < 0.001)." (PMID 29566741, 2018). "SLC7A5, SLC1A5, GLS and PIK3CA were significantly expressed in breast tumours with high expression of SLC3A2 (p < 0.001), while the low expression was associated with high levels of p-mTORC1 (p < 0.001)." (PMID 29545595, 2018). "Higher levels of β‐catenin expression in the normal glands of PIK3CA‐mutant mice, and reports that PIK3CA‐H1047R caused an expansion of the luminal progenitor population, led us to hypothesize that the Wnt signaling pathway is likely to be activated in the PIK3CA‐H1047R human breast tumors." (PMID 28296140, 2017). "Accordingly, the aim of the present study was to use NGS for the analysis of PIK3CA mutations to determine whether additional changes could be identified that might lead to better correlation of the clinicopathological characteristics of breast tumors with PIK3CA mutations." (PMID 26587011, 2015). "The gene coding for PDK1 is amplified in many breast tumors with PI3K pathway activation, including tumors with HER2 amplification, activating mutations in PIK3CA or PTEN inactivation." (PMID 21646685, 2011). "Helical domain mutations are associated with dramatically reduced overall and disease-free survival, whereas patients with kinase domain mutant breast tumors show enhanced survival as compared to patients with either wildtype or helical mutant PIK3CA." (PMID 21646685, 2011). "For example, breast tumors show mutation or loss of PTEN or both, amplification and activating mutations in PIK3CA, amplification of Akt2 and p70S6kinase, and overexpression of Akt3." (PMID 20569503, 2010). "In our study, we used quantitative real-time PCR, a very sensitive and far more accurate technique, to specifically quantitate the genomic copy number of PIK3CA not only in primary breast tumors but also in paired tissues." (PMID 16168105, 2005).
breast tumors (continued). "PIK3CA was also significantly expressed in breast tumours with high SLC1A5 expression (P = 0.005)." (PMID 39843491, 2025). "5-Fold cross-validation achieved an accuracy of 69.7% (sensitivity = 84.4%, specificity = 41.7%) pointing to factors other than PIK3CA genotype that could affect ω6 FA levels in breast tumor tissue." (PMID 39294437, 2024). "Since PIK3CA gene alterations are common in breast tumors, they represent rational drug targets." (PMID 38807154, 2024). "For example, some ERBB2+ and mutant PIK3CA breast tumors show elevated RHOC expression." (PMID 38807216, 2024). "Notably, most breast tumors present alterations in different components of the PI3K pathway, with the most frequent being PTEN loss and activating mutations in PIK3CA, which encodes the catalytic subunit alpha of PI3K7,8." (PMID 36792625, 2023). "PIK3CA was silenced by siPIK3CA to improve the breast tumor therapy outcome." (PMID 36678782, 2023). "HER2-low breast tumors also had significantly higher mutations rates in CBFB (p < 0.05), PIK3CA (p < 0.05), mitogen-activated protein kinase kinase kinase 1 (MAP3K1; p < 0.05), and AT-rich interaction domain 1A (ARID1A; p < 0.05) as compared with HER2-zero breast tumors." (PMID 35484593, 2022). "Somatic mutations in PIK3CA have been demonstrated to be associated with HR-positive (either ER-positive or PR-positive)/HER2−negative breast tumors." (PMID 32695676, 2020). "Besides well-known cases such as BRAF (V600E), KRas (G12D, G13D) or PIK3CA (G118D), we derived previously uncharacterized hotspot mutations such as SF3B1 (K700E) found in eight breast tumors and one leukemia sample." (PMID 31345222, 2019). "Also, there was a previous report at 2010 showed PIK3CA high expression in breast tumor tissue with IHC." (PMID 31554385, 2019). "In breast tumor tissue observed increase the PIK3CA mRNA expression in 47 patients out of 50 (94%)." (PMID 31554385, 2019). "We reported strong correlations between the distributions of PIK3CA impactful mutations and hormone receptor positivity in breast tumors, whereas this relationship did not seem to hold true for non-impactful mutations." (PMID 29636477, 2018). "Overall, proteogenomic analysis revealed that the dual activation of PIK3CA at the genomic level and AKTs at the protein level may be a common signature of breast tumours, affecting more than 20% of PDXs in this cohort." (PMID 28348404, 2017). "PIK3CA is known as a gene related malignant neoplasm of breast and inhibits apoptosis function." (PMID 27490120, 2016). "PIK3CA mutations and PTEN loss are considered to be nearly mutually exclusive in breast tumors, a characteristic shared by our series, as only four tumors presented concomitantly a PTEN deletion and a PIK3CA activating mutation (one in exon 9, three in exon 20)." (PMID 26680641, 2015).
breast tumors (continued). "Gene expression profiling of 249 ER-alpha+ breast tumors revealed that nineteen genes were differently expressed in PIK3CA-mutated tumors in comparison to samples lacking PIK3CA mutations." (PMID 25051360, 2014). "We found that 6124 probes were differentially expressed between breast tumors with and without PIK3CA mutations, with P values <0.05." (PMID 21209903, 2010). "Several studies suggest that PIK3CA mutations are more frequent in estrogen receptor alpha (ERα)-positive breast tumors (30–40%) than in ERα-negative breast tumors (10–20%)." (PMID 21209903, 2010). "Importantly, alpelisib “off-label” activating PIK3CA mutations (those not detected by therascreen®PIK3CA RGQ PCR Kit in SOLAR-1 trial) were seen in 388 (7.9%) of all breast tumors." (PMID 32983983, 2020). "It is now known that PIK3CA is mutationally activated in up to 40% of ER alpha-positive tumors; PTEN levels are decreased in a similar proportion, and AKT2 (up to 5%) and p70S6K (10-20%) may also be overexpressed by amplification in some breast tumors." (PMID 33299611, 2020). "Analysis of 965 primary breast tumors from TCGA RNA‐seq dataset showed that breast tumors harboring H1047R and other PIK3CA mutations (including E545K and E542K) have significant upregulation of AXIN2, HGF, STAT3, IGF‐1, and IGF‐2 mRNA compared with PIK3CA‐wild‐type and HER‐2‐amplified tumors." (PMID 28296140, 2017). "To identify relevant downstream target genes and signaling activated by aberrant PI3K/AKT pathway in breast tumors, we first analyzed gene expression with a pangenomic oligonucleotide microarray in a series of 43 ERα-positive tumors with and without PIK3CA mutations." (PMID 21209903, 2010). "In addition, targeting glutathione biosynthesis with BSO selectively sensitizes PIK3CA mutant breast tumors to cisplatin as compared to wild-type ones, indicating that impairing the antioxidant response could be an exploitable vulnerability in PI3K-driven tumors." (PMID 29868481, 2018). "Estimated using the ssGSEA (single sample gene set analysis) method, PIK3CA‐mutant breast tumors showed activated AKT, IGF1‐mTOR, and WNT canonical signaling pathways compared to PIK3CA‐wild‐type and HER2‐overexpressing tumors." (PMID 28296140, 2017). "We showed that hyperphosphorylation in ATP citrate lyase (ACL) occurs frequently in human breast tumors and correlates well with HER2+ and/or PIK3CA-mutant (HER2+/PIK3CAmut) status in breast tumor cell lines." (PMID 27015560, 2016). "Interestingly, we detected PIK3CA c.3140A>G (p.H1047R) hotspot activating mutation in a metastatic lymph node of a MBC case that did not harbor PIK3CA mutation in the corresponding primary breast tumor." (PMID 27765917, 2016). "One observation in support of this is that PIK3CA-activated breast tumours tend to be luminal, whereas PTEN-inactivated breast tumours tend to be basal-like; however, harbouring simultaneous events in both genes is not additively advantageous to cells." (PMID 26427375, 2015). "Conversely, the brain and lung metastases shared the hotspot PIK3CA E545K mutation as well as all three ESR1 mutations (E380Q, D273N, D351H), which were not present in the matched primary breast tumor." (PMID 37377606, 2023).
breast tumors (continued). "PIK3CA H1047R/L was the most common in HER2-low (n = 71) and HER2-positive (n = 46) breast tumors." (PMID 35484593, 2022). "The nature of these genetic lesions remains to be determined, but are not likely to include oncogenic PIK3CA mutations or PTEN inactivation, which have been shown to be mutually exclusive with AKT1(E17K), at least in breast tumors." (PMID 27004402, 2016). "Our STAR-FISH data showed that cells with PIK3CAH1047R are often present in untreated HER2+ breast tumors as minor subpopulations that increase in frequency after neoadjuvant chemotherapy with or without a HER2-targeted agent, implying that mutant PIK3CA might play a role in therapeutic resistance." (PMID 33886505, 2021).
melanoma (107 papers, 2008 to 2026). A malignant, usually aggressive tumor composed of atypical, neoplastic melanocytes. "In turn, the PIK3CA E545K mutation pre-existing in NRAS-driven melanoma was indicated as an aberration that caused resistance to MEK and CDK4/6 inhibitors in melanoma patients." (PMID 39340537, 2024). "We analysed the behaviour of the MAPK and PI3K–Akt pathways in the presence of the PIK3CA H1047R mutation in melanoma cells treated with targeted therapy." (PMID 35335966, 2022). "Taken together, our data showed that PI3K–Akt activation mediated by the PIK3CA H1047R mutation promotes the proliferation and resistance of melanoma cells treated with BRAF and MEK inhibitors." (PMID 35335966, 2022). "In melanoma, PTEN deletion or inactivating mutations are found in 12% of patients, and 3% of patients carried PIK3CA mutations [n = 471, TCGA-melanoma Firehose Legacy (cBioportal.org)]." (PMID 35806358, 2022). "We performed functional experiments on a melanoma model to evaluate the role of the PIK3CA H1047R mutation, a main enhancer of the Akt pathway, in drug resistance and evaluate the crosstalk existing between the MAPK and PI3K–Akt pathways." (PMID 35335966, 2022). "Similar findings were reported in a melanoma study in which one of eight tested cases had a PIK3CA mutation only present in the metastatic lesion." (PMID 34257602, 2021). "BRAF, MEK, NRAS, HRAS, KRAS, c-KIT, c-Met, VEGFR, PTEN, and PIK3CA mutations are common in melanoma." (PMID 34804979, 2021). "Usually, PIK3CA activating mutations are rare in melanoma with a frequency of 5%, despite the ability of activated PIK3CA (H1047R) to cooperate with BRAF V600E promoting melanomagenesis in mouse models." (PMID 32850962, 2020). "In this analysis BRAF, KIT, NRAS, and PIK3CA mutations were examined by next generation sequencing (NGS) in 446 melanomas in a clinical diagnostic setting." (PMID 31277584, 2019). "BRAF and NRAS-mutated melanomas showed a significantly lower incidence of coexisting mutations of different genes (10 and 8.1%, respectively) as compared to PIK3CA, HRAS and KIT-mutated melanomas (75, 67 and 36%; all P < .001)." (PMID 31277584, 2019). "Activating PIK3CA mutations affecting codons 542, 545 or 1047 were observed in 2 melanomas with a class-1 BRAF mutation and 1 melanoma with a class-3 BRAF mutation." (PMID 31277584, 2019). "Our study aimed to examine the associations between the clinical outcomes of malignant melanoma and some variants of SNPs in PIK3CA, PIK3R1 and VDR genes." (PMID 29100280, 2017). "We here assessed the prevalence of the coexistence of BRAF/NRAS and PIK3CA mutations in a series of melanoma samples." (PMID 25627962, 2015). "Melanoma cell lines with coexistence of PIK3CA and BRAF mutations were also investigated to evaluate the level of interference with the anti-proliferative effects of the BRAF-mutant inhibitor vemurafenib." (PMID 25627962, 2015). "An NSCLC specimen showed an additional KRAS p.V8I (c.22G > A) mutation in the same allele of p.G13D (c.38G > A) mutation (case P10) and a melanoma specimen showed an addition PIK3CA p.P75S (c.169C > T) mutation (case P8)." (PMID 26498038, 2015). "Among the analysed melanomas, 12/245 (4.9%) samples presented the coexistence of PIK3CA and BRAF/NRAS mutations." (PMID 25627962, 2015). "Although activating mutations of the p110 alpha isoform of PI3K (PIK3CA) also contribute to tumourigenesis in many types of cancer, they are found only at a low frequency in melanoma." (PMID 22475322, 2012). "In addition, PIK3CA mutations, typically rare in melanoma (< 5%), were observed in 21.7% of our patients." (PMID 40652269, 2025). "In melanoma, PIK3CA mutations are rare and occur in 2–3% of patients." (PMID 39340537, 2024).